IKZF4 (IKAROS family zinc finger 4)
Description:
DNA-binding protein that binds to the 5'GGGAATRCC-3' Ikaros-binding sequence. Transcriptional repressor. Interacts with SPI1 and MITF to repress transcription of the CTSK and ACP5 promoters via recruitment of corepressors SIN3A and CTBP2. May be involved in the development of central and peripheral nervous systems. Essential for the inhibitory function of regulatory T-cells (Treg). Mediates FOXP3-mediated gene silencing in regulatory T-cells (Treg) via recruitment of corepressor CTBP1 (By similarity).
Synonyms: ZNFN1A4; Eos
Tractability: PROTAC: UniProt records ubiquitination sites on it; ubiquitination databases record sites on it.
Gene: Protein-coding gene on chromosome 12 (56,007,430 to 56,038,435, forward strand). Ensembl gene ENSG00000123411.
Subcellular location: Nucleus
Subcellular location (Human Protein Atlas): Nuclear bodies; Nucleoplasm
Gene Ontology:
Molecular function: protein binding; protein domain specific binding; zinc ion binding; DNA-binding transcription factor activity; RNA polymerase II cis-regulatory region sequence-specific DNA binding; bHLH transcription factor binding; sequence-specific DNA binding
Biological process: protein homooligomerization; negative regulation of DNA-templated transcription; regulation of transcription by RNA polymerase II; regulation of DNA-templated transcription
Cellular component: nuclear body; nucleoplasm; nucleus; protein-containing complex
Genetic constraint (gnomAD): Loss-of-function variants: 11 observed, 46.41 expected, observed/expected ratio (o/e) 0.24, 90% interval 0.15 to 0.39. The upper end of that interval is the gene's LOEUF score, 0.39, which puts it in group 1 of 6, group 1 being the genes least tolerant of losing a copy. Missense variants: 557 observed, 792.16 expected, observed/expected ratio (o/e) 0.7, 90% interval 0.65 to 0.75. Synonymous variants: 298 observed, 304.56 expected, observed/expected ratio (o/e) 0.98, 90% interval 0.89 to 1.08.
Homologues: Orthologues: chimpanzee IKZF4 (100% identical), macaque IKZF4 (99% identical), dog IKZF4 (99% identical), rabbit IKZF4 (99% identical), guinea pig IKZF4 (98% identical), mouse Ikzf4 (95% identical), rat Ikzf4 (92% identical), pig IKZF4 (92% identical), tropical clawed frog ikzf4 (64% identical), zebrafish ikzf4 (56% identical), Drosophila melanogaster CG14442 (8% identical), Drosophila melanogaster CG14440 (4% identical). Paralogues in human: IKZF2 (48% identical), IKZF1 (44% identical), IKZF3 (38% identical), ZNF567 (15% identical), ZNF613 (14% identical), ZNF382 (14% identical), ZNF350 (14% identical), ZNF649 (13% identical), ZNF639 (13% identical), ZNF564 (11% identical), ZNF821 (10% identical).
Diseases named in the same sentence as IKZF4 in open-access papers:
IKZF4 is named in the same sentence as 28 diseases in open-access papers, as found by Europe PMC text mining. Sharing a sentence is not in itself a finding about the gene and the disease. The quoted sentences say what the papers report.
vitiligo (7 papers, 2016 to 2025). Generalized well circumscribed patches of leukoderma that are generally distributed over symmetric body locations and is due to autoimmune destruction of melanocytes. "IKZF4 maybe another biological candidate gene for vitiligo and influences the development of vitiligo." (PMID 26870082, 2016). "Our prioritization pipeline revealed genes like IKZF4 and CCR6 that are already well-characterized to play a significant functional role in the development of vitiligo as evident from Harmonizome Dataset and GeneMania, thus indicating reliability and reproducibility of our prioritization process." (PMID 36008553, 2022).
asthma (5 papers, 2022 to 2024). "Genetic variation of IKZF4 have been reported of association with both asthma in both European and East Asian." (PMID 35524249, 2022). "Five genes previously reported in a genome-wide association study (GWAS) on asthma, including TSLP, SLC9A4, PSMB8, IGSF5, and IKZF4 were demonstrated association in the asthma vs. control analysis." (PMID 35524249, 2022). "In our study, in addition to the associations with asthma, the gene IKZF4 showed nominal significance with obesity in the logistic regression analysis adjusted for asthma, implying IKZF4 variants might contribute to asthma through obesity." (PMID 35524249, 2022). "Three of the genes delineated clear heterogeneous effects between obese asthma and non-obese asthma, with IKZF4 and IGSF5 showing association with obese asthma, and SLC9A4 with non-obese asthma." (PMID 35524249, 2022). "The associations of IKZF4 and IGSF5 are only associated with obese asthma; and the association of SLC9A4 is only observed in non-obese asthma." (PMID 35524249, 2022). "In contrast to the associations of IKZF4 and IGSF5 seen in obese asthma, the genetic association of SLC9A4, encoded by the solute carrier family 9 member A4 gene, is only seen in non-obese asthma." (PMID 35524249, 2022).
diabetes (3 papers, 2021 to 2025). "Interestingly, a recent paper from the Belgian Diabetes Registry described that ERBB3/IKZF4 risk alleles increased the progression from single to multiple AABs, but this was seen only in female relatives." (PMID 35812428, 2022). "We selected SNPs rs2292239 and rs1701704, located near ERBB3/IKZF4, to investigate this in a cohort of autoAb+ FDRs followed by the Belgian Diabetes Registry (BDR)." (PMID 34448034, 2021). "The effect of ERBB3/IKZF4 genotypes and sex, on the progression of single autoantibody positivity to multiple autoantibody positivity and from multiple autoantibody positivity to diabetes, was studied by Kaplan–Meier analysis and multivariate Cox regression." (PMID 34448034, 2021).
Autoimmunity (1 paper, 2025). The occurrence of an immune reaction against the organism's own cells or tissues. "Additionally, FOXP3 and IKZF4, critical for regulatory T-cell function and immune tolerance, contribute to the suppression of autoimmunity." (PMID 39860439, 2025).
melanoma (1 paper, 2022). A malignant, usually aggressive tumor composed of atypical, neoplastic melanocytes. "Although the roles of other Ikaros family members such as IKZF4–5 in melanoma remain unclear, IKZF3 may serve as biomarkers for the outcomes of treatments for SKCM that achieve a positive clinical prognosis." (PMID 36353107, 2022).
type 1 diabetes (1 paper, 2021). "Genetic variation in the ERBB3/IKZF4 region was repeatedly associated with type 1 diabetes and used to improve prediction of islet autoimmunity and disease progression." (PMID 34448034, 2021). "SNPs of ERBB3 (rs2292239 T/G) and IKZF4 (rs1701704 G/T) were screened by allelic discrimination quantitative PCR assay in first-degree relatives of type 1 diabetes patients who had developed at least one circulating autoantibody." (PMID 34448034, 2021). "Our findings suggest that interaction between sex and ERBB3/IKZF4 may contribute to the post-pubertal male excess in type 1 diabetes." (PMID 34448034, 2021). "In siblings and offspring of type 1 diabetes patients, polymorphism in region ERBB3/IKZF4 may affect disease progression at the level of epitope spreading in female individuals." (PMID 34448034, 2021). "We examined whether the non-HLA susceptibility locus ERBB3/IKZF4 influences progression of type 1 diabetes stage specifically according to sex." (PMID 34448034, 2021). "The progression from multiple autoantibody positivity to type 1 diabetes appeared not to be influenced by ERBB3/IKZF4." (PMID 34448034, 2021).
viral infections (1 paper, 2025). "On the other hand, Ikaros zinc finger transcription factor Eos (Ikzf4) is a positive regulator of CD4+CTLs during viral infections, such as influenza A virus (IAV) infection." (PMID 41009359, 2025).
tumor (5 papers, 2020 to 2024). "CD4+ T cells isolated from tumor tissue downregulate granzymes B and H and upregulate genes associated with regulatory T cells (FOXP3, IKZF4, CD38, ISG15)." (PMID 37648263, 2023). "It has been reported that Ikzf4 and Il1r2 are preferentially expressed in Treg cells, especially tumor-infiltrating Treg cells." (PMID 33644036, 2020). "Treg-selective deletion of essential Treg factors such as Neuropilin-1 (Nrp-1), suppressor of cytokine signaling 1 (SOCS1), enhancer of zeste homolog 2 (EZH2), Eos (IKzf4), or CARMA1 leads to Foxp3 downregulation and inflammatory cytokine secretion, conferring resistance to tumor growth in the host." (PMID 33024109, 2020). "Moreover, among different tumor locations, Ikaros genes were expressed at the highest levels in regional lymph nodes, IKZF1 and IKZF3 were expressed at the lowest levels in distant metastases, and IKZF2, IKZF4, and IKZF5 were expressed at the lowest levels in the primary tumor." (PMID 36353107, 2022). "However, the associations of the OS, DSS, and PFI rates of patients with higher expression levels of IKZF4–5 were not significantly different, and patients who expressed high levels of IKZF1–3 experienced significantly longer DSS and longer tumor progression-free survival." (PMID 36353107, 2022).
IKZF4 also shares sentences with these, for which no sentence is quoted: allergic disease (2 papers); alopecia areata (2); autoimmune disease (2); Obesity (2); alopecia (1); ankylosing spondylitis (1); atopic eczema (1); breast carcinoma (1); cancer (1); Crohn disease (1); eczema (1); hepatocellular carcinoma (1); leukemia (1); primary biliary cholangitis (1); primary sclerosing cholangitis (1); psoriasis (1); rheumatoid arthritis (1); Sepsis (1); squamous cell carcinoma (1); ulcerative colitis (1).